MZF1 (myeloid zinc finger 1)
Diseases named in the same sentence as MZF1 in open-access papers (continued):
Sharing a sentence is not in itself a finding about the gene and the disease.
cancer (continued). "The expression levels of MZF1 and its protein partners were compared in normal and tumor samples using RNASeq data from cancer patients." (PMID 28018905, 2016). "The inhibitory effects of MZF-160–72 on tumorigenesis further demonstrated that this region of MZF-1 is essential for the formation of the MZF-1/Elk-1 interaction and transcriptional activation of PKCα which is highly expressed in cancer cells." (PMID 27542222, 2016). "A focus on SCAN domains in cancer is of notable interest if we consider that both SCAN-only regulatory proteins and a SCAN-only short isoform of mzf1 with disordered N- and C-terminal tails are known to play major roles in cancer biology." (PMID 28018905, 2016). "These include cancer-related genes, such as the myeloid zinc finger 1 (MZF1), an oncogenic transcription factor involved in the progression of many solid cancers." (PMID 28018905, 2016). "In the present study, we specifically considered the transcription factors Ets-like protein-1 (Elk-1) and myeloid zinc finger-1 (MZF-1), which regulate PKCα expression in cancer cells." (PMID 27542222, 2016). "The integration of information available about MZF1 biological partners in the same cancer studies is also crucial since these proteins can exert marked effects, contributing to reshape and modulate the MZF1-mediated effects in the cell." (PMID 28018905, 2016). "We investigated the protein-protein interaction network of MZF1 and how it is perturbed in different cancer types by the analyses of high-throughput proteomics and RNASeq data." (PMID 28018905, 2016). "One example of a SCAN zinc finger transcription factor with a crucial role in cancer is Myeloid Zinc Finger 1 (MZF1)." (PMID 28018905, 2016). "Our results highlight the need for more studies on MZF1 alterations in cancer with a specific focus on different cancer subtypes and other available clinical data." (PMID 28018905, 2016). "We integrated a plethora of different computational methods to unveil the role of MZF1 alterations in different cancer types." (PMID 28018905, 2016). "A NMR structure of the MZF1 SCAN domain [Protein Data Bank (PDB) entry: 2FI2;] in its dimeric form is publicly available and we here use it to study the cancer-related mutational landscape of MZF1." (PMID 28018905, 2016). "A complex and heterogeneous role of MZF1 in tumors is supported by studies in cellular and animal models of different types of cancer." (PMID 28018905, 2016). "Extensive research has highlighted MZF1’s potential as a novel biomarker, suggesting that it could not only aid in the early diagnosis of cancer but also offer new insights into cancer treatment strategies." (PMID 40655141, 2025). "Future investigations into MZF1 may provide deeper insights into its complex role in cancer pathogenesis and potentially pave the way for the development of novel therapeutic strategies, particularly in addressing issues related to drug resistance." (PMID 40655141, 2025). "Conversely, in other cancer types, particularly KIRC, genomic alterations and methylation status of MZF1 may be more closely associated with patient survival, underscoring its potential as a prognostic factor." (PMID 40655141, 2025). "The findings suggest that MZF1 not only serves as a prognostic predictor for cancer patients but also offers valuable insight into their potential response to immunotherapy, providing a theoretical foundation for the development of personalized treatment strategies." (PMID 40655141, 2025). "The experiment also assessed the impact of reduced MZF1 expression on cancer cell migration." (PMID 40655141, 2025). "In this study, MZF1 may serve as a novel pan-cancer prognostic biomarker, offering valuable insights into predicting responses to immunotherapy." (PMID 40655141, 2025). "Thus, as the understanding of MZF1 deepens, it is poised to play a pivotal role in the future of cancer immunotherapy, facilitating personalized and more effective treatment approaches." (PMID 40655141, 2025).
cancer (continued). "Such investigations could illuminate new therapeutic strategies aimed at harnessing MZF1’s regulatory capabilities to optimize cancer treatment and improve patient prognosis." (PMID 40655141, 2025). "Lastly, the knockdown of MZF1 can suppress cancer cell migration." (PMID 40655141, 2025). "The role of MZF1 across different cancers demonstrates considerable heterogeneity." (PMID 40655141, 2025). "For instance, drugs such as JNK Inhibitor VIII, Elesclomol, Docetaxel, Bleomycin, AZD6482, and 17−AAG showed a positive correlation with MZF1 expression, suggesting that MZF1 may enhance the anti-cancer efficacy of these drugs." (PMID 40655141, 2025). "Such research could pave the way for novel strategies to modulate MZF1 expression, thereby enhancing the effectiveness of immunotherapies and offering cancer patients more precise and effective therapeutic options." (PMID 40655141, 2025). "This suggests that MZF1 could serve as a valuable drug target or prognostic biomarker, aiding in predicting drug efficacy and optimizing anti-cancer treatment regimens." (PMID 40655141, 2025). "Based on drug sensitivity analyses from multiple databases (CellMiner, CTRP, and GDSC), along with further experimental exploration, gain a deeper understanding of the relationship between MZF1 and various therapeutic agents, as well as its potential in cancer treatment." (PMID 40655141, 2025). "In conclusion, MZF1 expression levels are significantly correlated with cancer cell proliferation and migration ability, indicating that MZF1 may play an important regulatory role in tumorigenesis and progression." (PMID 40655141, 2025). "This may suggest that the role of MZF1 in these cancer types involves more complex or distinct mechanisms." (PMID 40655141, 2025). "Considering that MZF1 and SIRT6 were differently expressed in NSCLC cell lines and normal lung epithelial cell lines and that the function of SIRT6 in cancers remains controversial, we first tried to elucidate the function of MZF1 and SIRT6 in A549 and H460 cells." (PMID 39224032, 2024). "Many studies have identified MZF1 as an oncogenic transcription factor and cancer stemness factor." (PMID 36982267, 2023). "It has been unclear whether the SCAND factors and MZF1 are involved in proteotoxic stress response in cancer." (PMID 36982267, 2023). "We next hypothesized that the repressive transcription factors SCAND1, SCAND2 and MZF1(ZSCAN6) would contribute to enhanced prognosis in cancer patients, whereas high expression of HSP90 genes would likely be involved in a poorer prognosis." (PMID 36982267, 2023). "Here we describe a mechanism of how cancer cells employ oncogenic growth factor signaling to promote uptake and utilization of extracellular cholesterol via Myeloid Zinc Finger 1 (MZF1)-mediated Niemann Pick C1 (NPC1) expression and upregulated macropinocytosis." (PMID 37420029, 2023). "Furthermore, FTO promotes cancer progression by regulating the expression of MZF1, and knockdown of FTO inhibits cell proliferation and invasion." (PMID 38089085, 2022). "MZF1 appears to serve different roles in different types of cancers." (PMID 36499054, 2022). "Our data suggest that SCAND1 and MZF1 might also regulate molecular chaperone expression and the cell stress response in cancer." (PMID 36552758, 2022). "We found that many of these transcription factors themselves had 5′UTRs that were enriched in binding sites for MZF-1, a transcription factor primarily known to be involved in regulating transcription in myeloid lineage precursors, and more recently in various cancers." (PMID 33897458, 2021). "Here we will summarize the recent literature on the role and function of another cancer-relevant zinc finger transcription factor, Myeloid Zinc Finger 1 (MZF1), and present reasoning for its potential targeting in cancer and discuss the possibilities of how to target it." (PMID 31963147, 2020).
cancer (continued). "In general, more research is still needed to increase the understanding of the detailed function of MZF1 in cancer, of the cellular cancer-promoting programs it regulates, the cancers where its inhibition would be most beneficial, and how it should be achieved." (PMID 31963147, 2020). "To confirm whether MZF1 is a transcription factor for N-cadherin expression in mesenchymally transitioned cancer cells, we generated stable MZF1 knockdown (MKD) HCE4 cells and TE2-CK2α30 cells using short hairpin RNA (shRNA)." (PMID 29540671, 2018). "We observed a marked variability in the levels of mzf1 among patients with same cancer types." (PMID 28018905, 2016). "Collectively, we integrated many computational approaches, ranging from simple empirical energy functions to all-atom microsecond molecular dynamics simulations and network analyses to unravel the effects of cancer-related substitutions in relation to MZF1 structure and interactions." (PMID 28018905, 2016). "The effects mediated by MZF1 seem to be strictly dependent on the cancer type." (PMID 28018905, 2016). "Our results show a complex and heterogeneous role of MZF1 and its interaction network in cancer." (PMID 28018905, 2016). "We further focused on MZF1 because of its significant role in cancer." (PMID 27764784, 2016). "Notably, MZF1 could play an instrumental role in the predictive framework for immune therapeutic responses across diverse cancer types." (PMID 40655141, 2025). "This evidence proves that TGF-β-mediated MZF1 may play a role in cancer stem cell transformation." (PMID 37174714, 2023). "This could be achieved for example via cancer-induced aberrant expression of MZF1." (PMID 31963147, 2020). "The results demonstrated a significant positive correlation between MZF1 CNV and mRNA expression across most cancer types, with particularly strong correlations observed in UCS, ACC, ESCA, and OV." (PMID 40655141, 2025). "Altogether, ALKBH7, MYCBP, MZF1, RRS1, and TUSC2 were reported to be involved in the development and progression of cancer, and dysregulation of these genes was known to be highly correlated with tumorigenesis." (PMID 37654657, 2023). "Overall, we found that ALKBH7, MYCBP, MZF1, RRS1, and TUSC2 were reported to be involved in the development and progression of cancer." (PMID 37654657, 2023). "Depletion of MZF1 was found to decrease the expression of FPN, as expected, but in turn this was shown to result in enhanced cancer cell growth in addition to increased cytoplasmic iron retention." (PMID 31963147, 2020). "In the present paper we describe for the first time in any type of cancer cells the negative regulation of IGF-IR gene expression by Ik-1 and MZF1 transcription factors." (PMID 25884514, 2015). "However, in certain cancers such as KICH, KIRC, and THYM, a significant positive correlation between MZF1 expression and the TME was observed." (PMID 40655141, 2025). "Moreover, Myeloid zinc finger 1 (MZF1) is a ZFP from the Krüppel family containing a SCAN domain and was found to be aberrantly expressed in several cancers." (PMID 36358661, 2022). "Even though evidence of the connection between MZF1 and EMT is increasing, it is still not clear if the role of MZF1 in EMT is cancer type-specific, or if MZF1 can have a more general role in the initiation and/or maintenance of EMT." (PMID 31963147, 2020). "Interestingly, overexpression of PADI driven by MZF1 and Sp1/Sp3 binding to the promoter region can citrullinate PKM2 and stimulate glycolysis in cancer cells." (PMID 32002016, 2020). "MZF1 is also central for the activation of the expression of Phosphoinositide -3-Kinase Regulatory Subunit 3 Gamma (PIK3R3), which is a regulatory subunit of PI3 kinase (PI3K) needed for PI3K signaling and is important for cancer cell proliferation." (PMID 31963147, 2020). "It was concluded that, unlike osteoblast, MZF1 binds preferentially to the distal MZF1 binding site of N-cadherin promoter in cancer cells." (PMID 29540671, 2018).
cancer (continued). "MZF1, SOX10 and ZEB1 shRNAs displayed strong effect on survival of cancer cells." (PMID 28423538, 2017). "Despite the many questions surrounding MZF1 and its role in cancer, no systematic studies have been devoted to understanding the structural and functional impact of cancer-related mutations involving this SCAN domain." (PMID 28018905, 2016). "MZF1 is a transcription factor that regulates ErbB2-induced invasion of breast cancer cells by inducing expression of cathepsin B (CTSB) and the outward transport of lysosomes to the plasma membrane, where the exocytosis of cathepsin B and other lysosomal hydrolases contribute to cancer invasion." (PMID 37420029, 2023). "Thus, the combination of two agents demonstrates an enhanced effect of anti-cancer activity in which 5-Aza-induced upregulations MUC17 and MZF1 may promote the sensitivity of NSCLC resistant cells to EGFR-TKIs." (PMID 36778111, 2023). "IGF1R, one of the members of the insulin/IGF system, was mostly expressed in foetal and cancer tissues 39 and three CpG islands are predicted in the promoter region of IGF1R which may combine large list of transcript factors including MZF1, TCFL5, USF1, ETS1 and SPIB." (PMID 33085184, 2020). "Furthermore, we have tested the hypothesis that the relationship between MZF1 and SCAND1 regulates CDC37 expression and thereby cancer growth." (PMID 31181782, 2019). "All MZF1 shRNAs, 4 out of 5 SOX10 shRNAs, and 2 of 3 ZEB1 shRNAs exhibited a strong effect on nearly all 212 cell lines, suggesting that these 3 TFs could be functionally essential in cancer cells." (PMID 28423538, 2017). "However, in certain cancers, such as GBM, KIRC, LGG, UCEC, and KIRP, elevated MZF1 expression did not significantly correlate with improved overall survival." (PMID 40655141, 2025).
infection (2 papers, 2017 to 2019). The state of being infected such as from the introduction of a foreign agent such as serum, vaccine, antigenic substance or organism. "In the present study, we see over-representation of TFBS for the putatively oncogenic MZF1 protein in genes downregulated after infection of resistant line 61 BMDMs." (PMID 30678299, 2019).
MZF1 also shares sentences with these, for which no sentence is quoted: head and neck cancer (3 papers); adenomyosis (1); autoimmune disease (1); cardiomyopathy (1); colon adenocarcinoma (1); COVID-19 (1); diabetes (1); diabetic nephropathy (1); graft versus host disease (1); haematological disorders (1); head and neck squamous cell carcinoma (1); inflammation (1); Kabuki syndrome (1); metastatic tumor (1); Nijmegen breakage syndrome (1); oral squamous cell carcinoma (1); osteogenesis imperfecta (1); rectum adenocarcinoma (1); renal clear cell carcinoma (1); sarcoma (1); skin cutaneous melanoma (1); squamous cell carcinoma (1); stomach cancer (1); testicular germ cell tumor (1).